HIP1 (huntingtin interacting protein 1)
Description:
Plays a role in clathrin-mediated endocytosis and trafficking. Involved in regulating AMPA receptor trafficking in the central nervous system in an NMDA-dependent manner (By similarity). Regulates presynaptic nerve terminal activity (By similarity). Enhances androgen receptor (AR)- mediated transcription. May act as a proapoptotic protein that induces cell death by acting through the intrinsic apoptosis pathway. Binds 3-phosphoinositides (via ENTH domain). May act through the ENTH domain to promote cell survival by stabilizing receptor tyrosine kinases following ligand-induced endocytosis. May play a functional role in the cell filament networks. May be required for differentiation, proliferation, and/or survival of somatic and germline progenitors.
Synonyms: HIP-I; ILWEQ; SHON; SHONbeta; SHONgamma
Tractability: PROTAC: ubiquitination databases record sites on it; its protein half-life has been measured.
Gene: Protein-coding gene on chromosome 7 (75,533,298 to 75,738,986, reverse strand). Ensembl gene ENSG00000127946.
Subcellular location: Cytoplasm; Nucleus; Endomembrane system; Cytoplasmic vesicle, clathrin-coated vesicle membrane
Subcellular location (Human Protein Atlas): Vesicles; Acrosome; Mid piece; Principal piece
Pathways (Reactome):
Disease: ALK mutants bind TKIs; Signaling by ALK fusions and activated point mutants
Vesicle-mediated transport: Clathrin-mediated endocytosis
Gene Ontology:
Molecular function: actin filament binding; AP-2 adaptor complex binding; clathrin binding; clathrin light chain binding; phosphatidylinositol binding; phosphatidylinositol-3,4-bisphosphate binding; phosphatidylinositol-3,5-bisphosphate binding; phosphatidylinositol-3-phosphate binding; phosphatidylinositol-4,5-bisphosphate binding; protein binding; protein heterodimerization activity; protein homodimerization activity; clathrin adaptor activity; epidermal growth factor receptor binding; glutamate receptor binding; structural constituent of cytoskeleton; actin binding; phospholipid binding
Biological process: apoptotic process; apoptotic signaling pathway; clathrin coat assembly; positive regulation of epidermal growth factor receptor signaling pathway; positive regulation of platelet-derived growth factor receptor-beta signaling pathway; positive regulation of receptor-mediated endocytosis; protein stabilization; regulation of apoptotic process; actin filament organization; endocytosis; neurotransmitter receptor transport; positive regulation of phosphatidylinositol 3-kinase/protein kinase B signal transduction; regulation of endocytosis; presynaptic modulation of chemical synaptic transmission; regulation of postsynaptic neurotransmitter receptor internalization
Cellular component: clathrin-coated vesicle; cytoplasm; Golgi apparatus; presynapse; cortical actin cytoskeleton; cytoskeleton; cytosol; membrane; nucleus; postsynapse; clathrin-coated vesicle membrane; endomembrane system; glutamatergic synapse; Schaffer collateral - CA1 synapse; synapse
Genetic constraint (gnomAD): Loss-of-function variants: 48 observed, 106.43 expected, observed/expected ratio (o/e) 0.45, 90% interval 0.36 to 0.57. The upper end of that interval is the gene's LOEUF score, 0.57, which puts it in group 2 of 6, group 1 being the genes least tolerant of losing a copy. Missense variants: 853 observed, 1,057.4 expected, observed/expected ratio (o/e) 0.81, 90% interval 0.76 to 0.85. Synonymous variants: 394 observed, 420.34 expected, observed/expected ratio (o/e) 0.94, 90% interval 0.86 to 1.02.
Cancer hallmarks: escaping programmed cell death (promotes)
Homologues: Orthologues: chimpanzee HIP1 (99% identical), macaque HIP1 (98% identical), pig HIP1 (91% identical), dog HIP1 (91% identical), guinea pig HIP1 (90% identical), rabbit HIP1 (89% identical), mouse Hip1 (88% identical), rat Hip1 (85% identical), zebrafish hip1 (67% identical), tropical clawed frog hip1 (61% identical), Caenorhabditis elegans hipr-1 (31% identical), Drosophila melanogaster Hip1 (31% identical), and 1 more. Paralogues in human: HIP1R (51% identical).
Diseases named in the same sentence as HIP1 in open-access papers:
HIP1 is named in the same sentence as 74 diseases in open-access papers, as found by Europe PMC text mining. Sharing a sentence is not in itself a finding about the gene and the disease. The quoted sentences say what the papers report.
Huntington disease (13 papers, 2009 to 2024). Huntington disease (HD) is a rare neurodegenerative disorder of the central nervous system characterized by unwanted choreatic movements, behavioral and psychiatric disturbances and dementia. "HIP1 is associated with Huntington’s disease and neuronal cell death through the intrinsic apoptotic pathway." (PMID 35682902, 2022). "HIP1 has been shown to be a direct interactor of huntingtin (the causal protein mutated in Huntington’s disease)." (PMID 31535203, 2020). "Our results also suggest the involvement of K48/K63 branched Ub in Huntington’s disease, as we identified the huntingtin-interacting protein HIP1 and UBR4, which has been linked to K11/K48 branched ubiquitination on mutant huntingtin, as specific interactors of Br Ub3." (PMID 38803224, 2024). "Huntingtin-interacting protein 1 (HIP1) interacts with the protein encoded by the gene mutated in Huntington’s disease, an inherited neurodegenerative disorder caused by expansion of the codon CAG in the Huntingtin gene and resulting in the translation of a polyglutamine tract in the protein." (PMID 34835114, 2021). "As a result of this multilayer analysis, genes related to Huntington’s disease are reported to be activated in RASFs in addition to known pathways, and invasion of RASFs is found to be suppressed by knockdown of the gene encoding Huntingtin Interacting Protein 1 (HIP1)." (PMID 33641680, 2021). "It is noteworthy that, in the present study, we identified huntingtin-interacting protein 1 (HIP1), which is an actin and clathrin binding protein that is involved in the pathogenesis of Huntington’s disease." (PMID 35806237, 2022). "In Huntington’s disease, HIP1’s pro-apoptotic activity has been proposed to play a role in the amplification of the cascade of cell death signals." (PMID 31535203, 2020). "In the context of Huntington Disease (HD), another epigenetic regulator of HIP1 and of other HD-related factors is miR-128a." (PMID 32069895, 2020). "Although soluble protein levels for MOBP and HIP1 in cerebellar white matter were not significantly different between MSA cases and controls, we found striking differences between MSA and other neurodegenerative diseases, including PD and Huntington's disease." (PMID 33368549, 2021).
prostate carcinoma (9 papers, 2015 to 2022). A carcinoma that arises from epithelial cells of the prostate gland. "Moreover, the overexpression of Huntingtin-interacting protein 1 (HIP1) has also been observed in prostate and colon tumor cells where HIP1 expression was significantly associated with prostate cancer progression and metastasis." (PMID 35631574, 2022). "As expected, HIP1 overexpression can partially counteract the effect of PCAL7 silence for prostate cancer cell migration." (PMID 33219721, 2021). "Stabilization of cellular HIP1 levels therefore plays an essential role for AR activation and AR‐dependent prostate cancer progression." (PMID 33219721, 2021). "HIP1 has also been found to be overexpressed in some cancers, including a subgroup of colorectal and prostate cancers." (PMID 30380781, 2018). "Although it was first implicated in cancer biology as part of a chromosomal translocation in leukemia, HIP1 represents a putative prognostic factor in human cancers, including prostate cancer and CRC." (PMID 29796160, 2018). "The similarities of high HIP1 expression between FAB subtype M4/M5 blasts and the prostate cancer cells suggest an analogous promoting metastasis role for HIP1 through regulations of cytoskeletal processes and integrin expression." (PMID 28452374, 2017). "Since HIP1 has a defined positive role to activate AR signaling pathway, the PCAL7‐HIP1 interaction may indirectly augment AR signaling and create a novel positive feedback loop in AR positive or dependent prostate cancer." (PMID 33219721, 2021). "Previous work has demonstrated that HIP1 protein is abundantly overexpressed in prostate cancer." (PMID 33219721, 2021). "The novel lncRNA PCAL7 can promote prostate cancer progression via stabilizing HIP1." (PMID 33219721, 2021). "Moreover, miR-23b/-27b suppressed CRPC cell migration, invasion, anchorage-independent growth, and tumor metastasis by downregulating Huntingtin interacting protein 1-related, while inhibition of miR23b/-27b in androgen-dependent prostate cancer cells increased migration and invasiveness." (PMID 34884984, 2021). "Since HIP1 decreases androgen receptor degradation, the AR‐PCAL7‐HIP1 axis creates a novel positive feedback loop to advance prostate cancer development." (PMID 33219721, 2021).
Arthritis (4 papers, 2019 to 2025). Inflammation of a joint. "Huntingtin-interacting protein-1 (HIP1) is a new arthritis severity gene implicated in the regulation of the invasive properties of rheumatoid arthritis (RA) fibroblast-like synoviocytes (FLS)." (PMID 38726004, 2024). "Studies involving HIP1 KO mouse models also indicated that loss of HIP1 protects against arthritis, likely due to reduced invasiveness of synovial fibroblasts and that HIP1 deficiency inhibits prostate tumorigenesis in vivo." (PMID 31671891, 2019). "Huntingtin-interacting protein 1-related (HIP1R) shares some function similarities with HIP1, and HIP1 regulates arthritis and RA fibroblast-like synoviocytes (FLS) invasiveness." (PMID 40214437, 2025). "FLS cell lines from arthritic DA (highly invasive) and from arthritis-protected congenic rats R6 (minimally invasive), which differ in an amino-acid changing HIP1 SNP, were cultured and lysed, and proteins were immunoprecipitated with an anti-HIP1 antibody." (PMID 38726004, 2024). "We have previously reported the discovery of a new arthritis severity gene, HIP1, in studies in mice and rats." (PMID 38726004, 2024). "We have recently identified Huntingtin-interacting protein 1 (HIP1) as a new mediator of arthritis severity and joint damage." (PMID 38726004, 2024). "Eleven proteins were detected only in the anti-HIP1 immunoprecipitates from DA, and two only in the R6 arthritis-resistant anti-HIP1 immunoprecipitates." (PMID 38726004, 2024). "These two rat strains were used in the positional identification of HIP1 as a new arthritis gene." (PMID 38726004, 2024). "Our previous studies showed that the Huntingtin-interacting protein 1 (HIP1) contributes to the invasive properties of RA fibroblast-like synoviocytes (FLSs) and of arthritis severity." (PMID 38974475, 2024).
lung adenocarcinoma (4 papers, 2017 to 2023). A carcinoma that arises from the lung and is characterized by the presence of malignant glandular epithelial cells. "Together, we identified a rare triple ALK fusion variant, ALK-LRRN2, LTBP1-ALK and HIP1-ALK, in a patient with lung adenocarcinoma." (PMID 34941039, 2021). "They observed that reduced expression of HIP1 in lung adenocarcinoma cells leads to development of late metastases and poor prognosis." (PMID 28452374, 2017).
brain tumors (3 papers, 2014 to 2021). "HIP1 gene encodes for Huntingtin interacting protein 1 (HIP1) that is predominantly expressed in brain and is proposed as a novel brain tumor marker that interacts with EGFR." (PMID 24628925, 2014). "HIP1 physically associates with EGFR and maintains its levels in brain tumors." (PMID 25050814, 2014).
colon cancer (3 papers, 2018 to 2022). "In colon cancer, the overexpression of endocytic adaptor Huntington interacting protein 1 (HIP1) is associated with poor clinical outcome." (PMID 29459716, 2018). "Particularly, HIP1 expression was demonstrated to be more elevated in prostate and colon cancers with respect to their normal counterparts." (PMID 32069895, 2020).
epilepsy (3 papers, 2014 to 2023). A brain disorder characterized by episodes of abnormally increased neuronal discharge resulting in transient episodes of sensory or motor neurological dysfunction, or psychic dysfunction. "For example, haploinsufficiency for HIP1 (deleted in JB) has been reported to be associated with neurological and neuropsychological deficits including epilepsy and autistic traits in other individuals with atypical deletions flanking the WSCR." (PMID 25057328, 2014). "The study of patients with intellectual disabilities, epilepsy and neurobehavioral problems found the deletion of HIP1 was sufficient to cause neurological disease and in subsequent mouse experiments, mice with a targeted mutation in the HIP1 gene showed neurodevelopmental disorders." (PMID 38136791, 2023). "Better understanding of the roles of HIP1 and YWHAG may eventually offer avenues for rational drug design, including antiseizure agents, in these patients who often present with drug-resistant epilepsy." (PMID 35481155, 2022).
Intellectual disability (3 papers, 2018 to 2023). "Two siblings, a younger brother with hypomyelinating leukodystrophy and an elder brother with severe intellectual disability and autistic features, had independent de novo variants of HSPD1 c.139T > G (p.Leu47Val) and HIP1 c.1393G > A (p.Glu465Lys), respectively." (PMID 30083362, 2018).
lung carcinoma (3 papers, 2017 to 2024). "Additionally, other studies have revealed elevated HIP1 expression in lung cancer, with HIP1 identified as a novel fusion partner of anaplastic lymphoma kinase." (PMID 38750426, 2024).
acute myeloid leukemia (2 papers, 2017 to 2021). Acute myeloid leukemia (AML) is a group of neoplasms arising from precursor cells committed to the myeloid cell-line differentiation. "Moreover, the overexpression of hip1 in bone marrow is associated with a lower overall survival in acute myeloid leukemia patients." (PMID 34277631, 2021).
breast carcinoma (2 papers, 2015 to 2019). "HIP1 is also overexpressed in several cancer tissues like breast cancer and possesses the oncogenic properties through BCL-2 and NF-κB pathways." (PMID 26296091, 2015).
Dementia with Lewy Bodies (2 papers, 2020 to 2021). "Interestingly, a study aiming to identify common DNA methylation changes across neurodegenerative diseases has shown shared changes in HIP1 (AD and Down syndrome) and MOBP (PD and Dementia with Lewy Bodies)." (PMID 31535203, 2020).
expressive language disorder (2 papers, 2020 to 2022). "Diseases associated with HIP1R (Huntingtin interacting protein 1 related) include expressive language disorder and cataract." (PMID 32508047, 2020). "Two reciprocal microduplications inclusive of HIP1 have been described in three children from two unrelated families who had neurobehavioral problems: one child had an expressive language disorder, and two children had attention deficit hyperactivity disorder and manifested aggressive behavior." (PMID 35627305, 2022).
Gait ataxia (2 papers, 2021 to 2022). A type of ataxia characterized by the impairment of the ability to coordinate the movements required for normal walking. "It is interesting to note that HIP1(−/−) mice develop a neurological phenotype by 3 months of age, including tremor and a gait ataxia secondary to a rigid thoracolumbar kyphosis accompanied by decreased assembly of endocytic protein complexes on liposomal membranes." (PMID 33368549, 2021). "While HIP1R has not been implicated in synaptic plasticity or the endocytosis of postsynaptic glutamate receptors before, mice lacking HIP1 display reduced LTD and suffer from progressive neurological defects culminating in tremor, gait ataxia, and premature death." (PMID 35613266, 2022).
HIV-1 infection (2 papers, 2021 to 2022). The type species of lentivirus and the etiologic agent of acquired immunodeficiency syndrome (AIDS). "The Huntingtin-interacting protein 1 (HIP1) was identified as a novel host factor involved in Vpr-induced G2 arrest and HIV-1 infection in macrophages." (PMID 35746791, 2022). "This study identifies HIP1 as a factor promoting Vpr-induced G2 arrest and HIV-1 infection in macrophages." (PMID 34835114, 2021). "In summary, the results of the present study suggest that HIP1 augments Vpr-induced G2 arrest and HIV-1 infection in macrophages and that HIP1 interacts with Vpr." (PMID 34835114, 2021). "In the present study, we showed that compared to that with Vpr-deleted HIV-1, HIP1 knockdown slightly but effectively inhibited WT HIV-1 infection in macrophages." (PMID 34835114, 2021). "Although HIP1 slightly but efficiently enhanced WT HIV-1 infection in macrophages relative to that by Vpr-deleted HIV-1, the associated mechanism(s) remain to be elucidated." (PMID 34835114, 2021). "Future investigations are required to determine the exact roles of HIP1 in Vpr-induced G2 arrest and HIV-1 infection in macrophages, as well as to provide insights into correlations between the two functions of Vpr." (PMID 34835114, 2021). "Screening results and a further validation experiment identified HIP1 as a novel host factor involved in Vpr-induced G2 arrest, after which we examined the effect of HIP1 knockdown on HIV-1 infection in macrophages." (PMID 34835114, 2021). "However, whether Vpr-induced G2 arrest and Vpr-mediated enhancement of HIV-1 infection requires the interaction between HIP1 and Vpr needs to be clarified." (PMID 34835114, 2021). "Therefore, it is possible that HIP1 also contributes to efficient HIV-1 infection in macrophages." (PMID 34835114, 2021). "Furthermore, HIP1 knockdown suppressed HIV-1 infection in monocyte-derived macrophages." (PMID 34835114, 2021). "Furthermore, we revealed that HIP1 contributes to efficient HIV-1 infection in macrophages." (PMID 34835114, 2021). "Even if the interaction between HIP1 and Vpr is not necessary for efficient Vpr-induced G2 arrest and HIV-1 infection in macrophages, the presence of HIP1 might affect the interaction between Vpr and other host proteins." (PMID 34835114, 2021). "However, it is not clear whether Vpr requires interaction with HIP1 to induce G2 arrest and facilitate HIV-1 infection in macrophages." (PMID 34835114, 2021).
learning disabilities (2 papers, 2022). "However, several studies have shown that ZNF717, HIP1, and several genes from the PRAME (Preferentially Expressed Antigen In Melanoma) family might be involved in cognitive development, learning disorders, and developmental disorders with autistic features." (PMID 35627305, 2022).
leukemia (2 papers, 2017 to 2018). A malignant (clonal) hematologic disorder, involving hematopoietic stem cells and characterized by the presence of primitive or atypical myeloid or lymphoid cells in the bone marrow and the blood. "Huntingtin interacting protein 1 (HIP1) is an endocytic protein which is overexpressed in a variety of human cancers and involved in cancer-causing translocation in leukemia." (PMID 28452374, 2017). "The relevance of high levels of HIP1 expression to the poor survival suggests that HIP1 may be functionally important for maintaining the continuous proliferation of leukemia cells." (PMID 28452374, 2017). "Quantitative RT-PCR analysis showed that siRNA treatment resulted in approximately 83% and 63% knockdown of HIP1 mRNA expression in THP-1 and Kasumi-1 leukemia cells after 72 hours compared to negative control." (PMID 28452374, 2017).
melanoma (2 papers, 2022 to 2025). A malignant, usually aggressive tumor composed of atypical, neoplastic melanocytes. "In support of this increase, the analysis of GLI target genes over time (24 and 48 h) showed that MEK5DD induced the expression of PTCH1 and HIP1 mRNA already at 24 h in melanoma cells." (PMID 39998753, 2025). "Q-PCR analysis showed that the expression of two GLI target genes, PTCH1 and HIP1, is significantly reduced by ERK5 silencing, suggesting that ERK5 regulates not only the expression but also GLI transcriptional activity in melanoma cells." (PMID 39998753, 2025).